UBQLN2 (ubiquilin 2)
Description:
Plays an important role in the regulation of different protein degradation mechanisms and pathways including ubiquitin-proteasome system (UPS), autophagy and the endoplasmic reticulum-associated protein degradation (ERAD) pathway. Mediates the proteasomal targeting of misfolded or accumulated proteins for degradation by binding (via UBA domain) to their polyubiquitin chains and by interacting (via ubiquitin-like domain) with the subunits of the proteasome. Plays a role in the ERAD pathway via its interaction with ER-localized proteins FAF2/UBXD8 and HERPUD1 and may form a link between the polyubiquitinated ERAD substrates and the proteasome. Involved in the regulation of macroautophagy and autophagosome formation; required for maturation of autophagy-related protein LC3 from the cytosolic form LC3-I to the membrane-bound form LC3-II and may assist in the maturation of autophagosomes to autolysosomes by mediating autophagosome-lysosome fusion. Negatively regulates the endocytosis of GPCR receptors: AVPR2 and ADRB2, by specifically reducing the rate at which receptor-arrestin complexes concentrate in clathrin-coated pits (CCPs).
Synonyms: PLIC-2; N4BP4; PLIC2; HRIHFB2157; Chap1; Dsk2; RIHFB2157; LIC-2; CHAP1/DSK2; ALS15
Tractability: Antibody: its Gene Ontology location is reachable by antibodies, with high confidence. PROTAC: ubiquitination databases record sites on it; its protein half-life has been measured.
Gene: Protein-coding gene on chromosome X (56,563,627 to 56,567,868, forward strand). Ensembl gene ENSG00000188021.
Subcellular location: Cytoplasm; Nucleus; Membrane; Cytoplasmic vesicle, autophagosome
Subcellular location (Human Protein Atlas): Cytosol; Plasma membrane
Pathways (Reactome):
Vesicle-mediated transport: Cargo recognition for clathrin-mediated endocytosis
Gene Ontology:
Molecular function: identical protein binding; molecular condensate scaffold activity; protein binding
Biological process: ERAD pathway; negative regulation of clathrin-dependent endocytosis; negative regulation of G protein-coupled receptor internalization; positive regulation of ERAD pathway; regulation of autophagosome assembly; regulation of macroautophagy; autophagosome assembly; ubiquitin-dependent protein catabolic process; negative regulation of transport
Cellular component: cytoplasm; cytosol; nucleus; membrane; autophagosome
Gene-disease validity (ClinGen):
ClinGen rates the evidence that UBQLN2 causes each of these diseases.
amyotrophic lateral sclerosis type 15 (X-linked): Definitive. Any amyotrophic lateral sclerosis in which the cause of the disease is a mutation in the UBQLN2 gene.
Homologues: Orthologues: macaque UBQLN2 (99% identical), guinea pig UBQLN2 (96% identical), rabbit UBQLN2 (96% identical), mouse Ubqln2 (89% identical), rat Ubqln2 (88% identical), chimpanzee UBQLN2 (88% identical), pig UBQLN2 (85% identical), Drosophila melanogaster CG31528 (16% identical). Paralogues in human: UBQLN1 (76% identical), UBQLN4 (56% identical), UBQLN3 (43% identical), UBQLNL (24% identical), UBL7 (17% identical).
Diseases named in the same sentence as UBQLN2 in open-access papers:
UBQLN2 is named in the same sentence as 49 diseases in open-access papers, as found by Europe PMC text mining. Sharing a sentence is not in itself a finding about the gene and the disease. The quoted sentences say what the papers report.
amyotrophic lateral sclerosis (53 papers, 2013 to 2026). Amyotrophic lateral sclerosis (ALS) is a neurodegenerative disease characterized by progressive muscular paralysis reflecting degeneration of motor neurons in the primary motor cortex, corticospinal tracts, brainstem and spinal cord. "Ubiquilins are molecular chaperones that play multifaceted roles in proteostasis, with point mutations in UBQLN2 leading to altered phase-separation properties and amyotrophic lateral sclerosis (ALS)." (PMID 41862640, 2026). "UBQLN2 has also gained recent attention as gene variants are associated with a familial form of amyotrophic lateral sclerosis with frontotemporal dementia." (PMID 41234208, 2025). "Ubiquilin-2 (UBQLN2) is a ubiquitin (Ub)-binding shuttle protein that is mutated in X-linked forms of amyotrophic lateral sclerosis (ALS) and frontotemporal dementia (FTD)." (PMID 41561437, 2025). "While UBQLN2 has been investigated in relation to the presence of mutations in the UBQLN2 gene associated with amyotrophic lateral sclerosis (ALS)/FTD, the number of studies on sporadic FTD is still small." (PMID 38256197, 2024). "It is reported that UBQLN2 is associated with a variety of neurological diseases, including polyglutamine disease, Alzheimer's disease, and amyotrophic lateral sclerosis (ALS)." (PMID 36644234, 2023). "The ubiquilin‐like protein ubiquilin 2 (UBQLN2) is associated with amyotrophic lateral sclerosis and frontotemporal degeneration (ALS/FTD)." (PMID 34750982, 2022). "UBQLN2 is another gene that encodes for ubiquitin-like protein ubiquitin two and is responsible for dominantly inherited, chromosome-X-linked amyotrophic lateral sclerosis (ALS)." (PMID 36017501, 2022). "A recent study showed that overexpression of UBQLN1 reduces neuropathology in a mouse model of amyotrophic lateral sclerosis with frontotemporal dementia (ALS/FTD) that contains a mutation in UBQLN2, a gene that encode an ubiquilin-1 homolog protein." (PMID 35401099, 2022). "UBQLN2 mutations are genetically linked to the neurodegenerative disorders amyotrophic lateral sclerosis and frontotemporal dementia (ALS/FTD)." (PMID 35777956, 2022). "Protein aggregation is one of the core features in both ubiquilin-2 (UBQLN2)-associated amyotrophic lateral sclerosis and frontotemporal degeneration (ALS/FTD), a phenomenon that has been well replicated in transgenic rodents." (PMID 33919255, 2021). "Mutations in the autophagy receptor Ubiquilin 2 (UBQLN2) have been associated with amyotrophic lateral sclerosis and frontotemporal degeneration (ALS/FTD)." (PMID 32413959, 2020). "UBQLN2 received much attention after the discovery of gene mutations in amyotrophic lateral sclerosis and frontotemporal dementia (ALS/FTD)." (PMID 31319884, 2019). "Analysis of functionally linked amyotrophic lateral sclerosis proteins revealed recruitment of p62, ubiquilin-2, and optineurin to TDP-43 aggregates." (PMID 28724966, 2017). "The UBQLN4 homologs UBQLN1 and UBQLN2 have been implicated in the pathogenesis of neurodegenerative diseases, i.e. Parkinson’s, Alzheimer’s, Huntington's, and amyotrophic lateral sclerosis/frontotemporal dementia." (PMID 26990090, 2016). "Mutations in the gene encoding Ubiquilin-2 (UBQLN2) are linked to amyotrophic lateral sclerosis (ALS) and frontotemporal dementia (FTD)." (PMID 26521126, 2015). "Interest in the proteins has been heightened by the discovery that gene mutations in UBQLN2 cause dominant inheritance of amyotrophic lateral sclerosis (ALS)." (PMID 26075709, 2015). "UBQLN2 mutations have recently been associated with familial forms of amyotrophic lateral sclerosis (ALS) and ALS-dementia." (PMID 26152284, 2015). "A recent study identified mutations in ubiquilin-2 as causative of a familial form of ALS (Amyotrophic lateral sclerosis)." (PMID 25245095, 2014). "Notably, mutations in the UBQLN2 gene are linked to amyotrophic lateral sclerosis (ALS) and frontotemporal lobar degeneration." (PMID 32585960, 2020).
amyotrophic lateral sclerosis (continued). "Furthermore, mutations in UBQLN2 have recently been detected in familial cases of amyotrophic lateral sclerosis (FALS) and frontotemporal lobar dementia (FTLD)." (PMID 32867756, 2020). "Mutations in the gene involved in the UPS pathway have been reported in neurodegenerative diseases, such as Parkin, an E3 ligase, in Parkinson’s disease and UBQLN2, a ubiquitin-like protein, in dominant X-linked juvenile and adult onset amyotrophic lateral sclerosis." (PMID 24312598, 2013). "In particular, mutation of UBQLN2 causes a familial form of amyotrophic lateral sclerosis (ALS)/ frontotemporal dementia (FTD)." (PMID 40663766, 2025). "In particular, point mutations of UBQLN2 cause an X-linked, dominant form of amyotrophic lateral sclerosis (ALS), ALS with frontotemporal dementia (ALS/FTD), or FTD." (PMID 40663766, 2025). "Missense UBQLN2 mutations also cause X-linked amyotrophic lateral sclerosis (ALS) and frontotemporal dementia (FTD)." (PMID 38472280, 2024). "The PABPC1 gene has been associated with the UBQLN2 gene, one of the key genes linked to amyotrophic lateral sclerosis (ALS)." (PMID 38540795, 2024). "ATP6V1G1 overexpression due to UBQLN2 mutations has been found to cause amyotrophic lateral sclerosis (ALS), frontotemporal dementia (FTD), and other neurodegeneration." (PMID 39621600, 2024). "Mutations in UBQLN2 have been linked to amyotrophic lateral sclerosis and its variant with frontotemporal lobar dementia (ALS/FTLD)." (PMID 38028759, 2023). "To illustrate this point, we have analyzed mutations in droplet-forming proteins, FUS (G156E, G187S), TDP-43 (A321V, A315T), TAU (P301L), TIA-1 (E384K), hnRNPA2 (D214V, D290V), UBQLN2 (P506T), which are associated with amyotrophic lateral sclerosis (ALS)." (PMID 36416856, 2022). "Another important shuttle protein is UBQLN2, which has been found to have amyotrophic lateral sclerosis (ALS)-causing mutations." (PMID 33809923, 2021). "Mutations in UBQLN2 cause a rare familial X-linked neurodegenerative disease belonging to the amyotrophic lateral sclerosis/frontotemporal dementia (ALS/FTD) spectrum." (PMID 33431932, 2021). "Another example is Amyotrophic Lateral Sclerosis (ALS), which can be caused by loss-of-function mutations in the UBQLN2/4 genes." (PMID 32903821, 2020). "Missense mutations in UBQLN2 cause X-linked dominant inheritance of amyotrophic lateral sclerosis with frontotemporal dementia (ALS/FTD)." (PMID 33028421, 2020). "Since 2011, mutation in a human UBQLN2 gene has been found to be associated with ALS/FTD (Amyotrophic Lateral Sclerosis/Frontotemporal dementia), the fatal neurodegenerative disease that progressively affected neuronal cells in both brain and spinal cord." (PMID 32867756, 2020). "The P497S mutation is one of several missense mutations in UBQLN2 that are linked to development of amyotrophic lateral sclerosis (ALS) alone or together with frontotemporal dementia (FTD)." (PMID 33028421, 2020). "It has been known that UBQLN2 gene is associated with amyotrophic lateral sclerosis (ALS) and ALS with frontotemporal dementia (FTD)." (PMID 28125704, 2017). "Mutations in the UBQLN2 gene, which encodes a member of the ubiquitin-like protein family (ubiquilin-2), have been identified in patients with dominant X-linked amyotrophic lateral sclerosis (ALS) and ALS with frontotemporal dementia (FTD)." (PMID 28125704, 2017). "The homolog UBQLN2 (ubiquilin-2) on the X chromosome has several gender-independent dominant mutations in a collagen-like proline-X-X repeat that cause ALS-FTD (amyotrophic lateral sclerosis-frontotemporal dementia)." (PMID 26990090, 2016). "Recently, mutations in the UBQLN 2 gene encoding ubiquilin 2 have been identified in X-linked amyotrophic lateral sclerosis (ALS)." (PMID 24086754, 2013). "Mutations in the ubiquitin (Ub) chaperone Ubiquilin 2 (UBQLN2) cause X-linked forms of amyotrophic lateral sclerosis (ALS) and frontotemporal dementia (FTD) through unknown mechanisms." (PMID 37039476, 2023).
amyotrophic lateral sclerosis (continued). "(A) Schematic of UBQLN2 and amyotrophic lateral sclerosis (ALS)-associated mutations." (PMID 37039476, 2023). "This is exemplified by UBQLN2 (ubiquilin-2), which was first found in amyotrophic lateral sclerosis (ALS)." (PMID 34440758, 2021). "UBQLN2 mutations result in familial amyotrophic lateral sclerosis (ALS)/frontotemporal dementia in humans through an unknown mechanism." (PMID 33277362, 2021). "Four genes linked to familial cases of amyotrophic lateral sclerosis were investigated for antisense transcription: SOD1, FUS, TARDBP, and UBQLN2." (PMID 30610612, 2019). "Mutations of Ubiquilin 2 (UBQLN2) or TANK-binding kinase 1 (TBK1) are associated with amyotrophic lateral sclerosis and frontotemporal degeneration (ALS/FTD)." (PMID 32413959, 2020). "Mutations in UBQLN2 cause an X-linked form of motor neurone disease [MND, or amyotrophic lateral sclerosis (ALS)], while mutations in UBQLN1 are associated with MND as well as Alzheimer’s disease." (PMID 27137187, 2016). "In amyotrophic lateral sclerosis (ALS), several polypeptides are inclined to misfold and aggregate, such as Tar DNA binding protein-43 (TDP-43), superoxide dismutase 1 (SOD1) and ubiquilin-2." (PMID 37107340, 2023). "Mutations in the human Ubiquilin 2 gene are associated with neurodegenerative diseases such as amyotrophic lateral sclerosis (ALS) with or without frontotemporal dementia (FTD), the fatal neurodegenerative disease that progressively affected neuronal cells in both brain and spinal cord." (PMID 32867756, 2020). "In mice, loss of SCYL1 function leads to an early onset motor neuron disorder with characteristic features of amyotrophic lateral sclerosis (ALS), including mislocalization of TDP43 and ubiquilin-2 in cytoplasmic aggregates in spinal motor neurons." (PMID 28570664, 2017).
frontotemporal dementia (31 papers, 2013 to 2025). Frontotemporal dementia (FTD) comprises a group of neurodegenerative disorders, characterized by progressive changes in behavior, executive dysfunction and language impairment, as a result of degeneration of the medial prefrontal and frontoinsular cortices. "Interest in ubiquilin function was greatly stimulated by the discovery that dominant mutations in UBQLN2 cause X-linked ALS/frontotemporal dementia (FTD)." (PMID 37039476, 2023). "Mutations in UBQLN2 were also described in other neurological disorders such as frontotemporal dementia (FTD) and spastic paraplegia." (PMID 30377984, 2019). "In 2011, mutations in the UBQLN2 gene were identified in families with both ALS and frontotemporal dementia (FTD) and have since been linked to ubiquitinated TDP43 inclusion pathology." (PMID 39628898, 2024). "Frontotemporal dementia (FTD) is the most common type of dementia associated with UBQLN2." (PMID 34946884, 2021). "Mutations in UBQLN2 cause a heritable, X-linked, dominant form of ALS with frontotemporal dementia in humans." (PMID 33277362, 2021). "Ubiquilin-2 (UBQLN2) mutations lead to familial amyotrophic lateral sclerosis (FALS)/and frontotemporal dementia (FTLD) through unknown mechanisms." (PMID 36232630, 2022). "For example, several genes causing ALS and/or frontotemporal dementia (C9orf72, VCP, SQSTM1, OPTN, UBQLN2, GRN, CHMP2B) affect the autophagic machinery; and some Alzheimer’s Disease genes (APOE, TREM2, CD33, ABCA7) are preferentially or exclusively expressed in microglia." (PMID 33892821, 2021). "The strongest connection of UBQLNs to neurodegenerative disease is between UBQLN2 and ALS with frontotemporal dementia (FTD)." (PMID 40663766, 2025). "Up to 15% of ALS patients also develop signs of frontotemporal dementia (FTD) and several genes, including C9ORF72, TDP-43, VCP, SQSTM1, OPTN, UBQLN2 and TBK1, contribute to the etiology of both ALS and FTD." (PMID 37220877, 2023). "In the present study, we investigate whether ubiquilin 2 is connected with tau pathology in Alzheimer’s disease (AD), supranuclear palsy (PSP) and Pick’s disease (PiD) and familial cases with frontotemporal dementia and parkinsonism linked to chromosome 17 (FTDP-17)." (PMID 24086754, 2013). "Given the patient’s family history of frontotemporal dementia (FTD) in a maternal uncle, the genetic analysis was extended to include the most common genes associated with FTD (TARDBP, GRN, TBK1, CHMP2B, SQSTM1, UBQLN2, VCP and MAPT) but no additional variants of clinical significance were detected." (PMID 40659544, 2025).
dementia (20 papers, 2012 to 2024). Loss of intellectual abilities interfering with an individual's social and occupational functions. "UBQLN2 and ubiquitin also co-localize in inclusions of the hippocampus in brain tissue from dementia-linked UBQLN2 mutation." (PMID 24915640, 2014). "Ubiquilin 2 positive inclusions were also found in sporadic cases of ALS and ALS/dementia, which together present approximately 90% of the patients indicating a causative role for ubiquilin 2 in a broad spectrum of ALS subtypes." (PMID 24086754, 2013). "In ALS, ubiquilin 2 mutations have been identified in families afflicted with ALS/dementia." (PMID 24086754, 2013). "Ubiquitin-like protein, specifically ubiquilin 2 (UBQLN2), mutations have been associated with X-linked dominant ALS and ALS/dementia in a multigenerational study involving five families with a rare occurrence of JALS." (PMID 34946884, 2021). "Mutations in UBQLN2 which encodes the ubiquitin-like protein, ubiquilin-2, are associated with X-linked ALS and ALS-dementia." (PMID 28512398, 2017). "One of them is mutations in UBQLN2, which encodes a ubiquitin-like protein, ubiquilin 2, cause dominantly inherited chromosome X-linked ALS and ALS/dementia." (PMID 26317018, 2013). "Missense mutations in the UBQLN2 gene are identified in some cases of dominantly inherited, chromosome-X-linked ALS with dementia." (PMID 22898310, 2012). "The proteasomal shuttle factor ubiquilin 2 (UBQLN2) contains the N-terminal ubiquitin-like (UBL) and C-terminal UBA domains, and mutations in the Pro-rich (PXX) region of UBQLN2 cause dominant X-linked ALS and ALS/dementia." (PMID 36726375, 2023). "Of the 40 individuals with UBQLN2 mutations, three individuals had onset of symptoms prior to age 24; one with classical ALS findings, one with ALS combined with FTD, and one described as having a combination of upper motor neuron signs and dementia." (PMID 34946884, 2021). "Mutations in UBQLN2 cause X-linked ALS and ALS with dementia." (PMID 34303705, 2021). "Mutations in ubiquilin-2 (UBQLN2) cause X-linked juvenile and adult-onset ALS and ALS/dementia." (PMID 30721407, 2019). "Furthermore, ubiquilin 2 is associated with inclusions in familial and sporadic ALS/dementia, synucleinopathies and polyglutamine diseases." (PMID 24086754, 2013). "In the present study, we investigated whether ubiquilin 2 pathology described for ALS/dementia is also present in tau-related dementias (AD and FTD-tau), which are characterized by inclusions comprised of hyperphosphorylated tau." (PMID 24086754, 2013). "Ubiquilin 2 has recently been linked to intraneuronal inclusions in ALS and ALS/dementia." (PMID 24086754, 2013). "In cases with ALS-dementia with or without UBQLN2 mutations, UBQLN2-positive inclusions are found in the hippocampus which are absent in ALS cases without dementia indicating that UBQLN2 aggregation and neurodegeneration are linked." (PMID 23673820, 2013). "These last findings may explain the involvement of UBQLN2 in the three distinct forms of dementia." (PMID 38256197, 2024). "Mutations in UBQLN2 have been identified in ALS patients with or without dementia." (PMID 28463112, 2017). "Interestingly, mutations in UBQLN2 were found to cause chromosome X-linked ALS and ALS/dementia." (PMID 23475610, 2013). "Strikingly, ubiquilin 2 pathology in the hippocampus of patients with familial and sporadic ALS was correlated with dementia." (PMID 24086754, 2013). "Furthermore, our SBT mouse models demonstrate a powerful and complementary approach to traditional transgenics that will allow further dissection of pathological mechanisms of ubiquilin-2 mutants and their role in development of ALS and ALS-dementia." (PMID 26152284, 2015). "UBQLN2 inclusions are also found in fALS, sALS and ALS-dementia cases without UBQLN2 mutations." (PMID 23941283, 2013).